TM4SF18 (transmembrane 4 L six family member 18)
Synonyms: L6D
Tractability: Antibody: UniProt predicts a signal peptide or a membrane-spanning region; the Human Protein Atlas places it where antibodies can reach.
Gene: Protein-coding gene on chromosome 3 (149,318,498 to 149,334,414, reverse strand). Ensembl gene ENSG00000163762.
Subcellular location: Membrane
Subcellular location (Human Protein Atlas): Plasma membrane
Gene Ontology:
Molecular function: protein binding
Cellular component: membrane
Genetic constraint (gnomAD): Loss-of-function variants: 19 observed, 19.55 expected, observed/expected ratio (o/e) 0.97, 90% interval 0.68 to 1.43. The upper end of that interval is the gene's LOEUF score, 1.43, which puts it in group 5 of 6, group 1 being the genes least tolerant of losing a copy. Missense variants: 216 observed, 212.05 expected, observed/expected ratio (o/e) 1.02, 90% interval 0.91 to 1.14. Synonymous variants: 76 observed, 80.43 expected, observed/expected ratio (o/e) 0.94, 90% interval 0.78 to 1.14.
Homologues: Orthologues: chimpanzee TM4SF18 (100% identical), macaque TM4SF18 (97% identical), dog TM4SF18 (91% identical), pig TM4SF18 (90% identical), rabbit TM4SF18 (89% identical), guinea pig TM4SF18 (87% identical), tropical clawed frog tm4sf18 (56% identical), zebrafish tm4sf18 (38% identical). Paralogues in human: TM4SF1 (45% identical), TM4SF4 (37% identical), TM4SF5 (33% identical), TM4SF19 (26% identical), TM4SF20 (22% identical).
Diseases named in the same sentence as TM4SF18 in open-access papers:
TM4SF18 is named in the same sentence as 20 diseases in open-access papers, as found by Europe PMC text mining. Sharing a sentence is not in itself a finding about the gene and the disease. The quoted sentences say what the papers report.
gastric cancer (2 papers, 2022 to 2025). A primary or metastatic malignant neoplasm involving the stomach. "Previous research demonstrates that TM4SF18 upregulation promotes proliferation, migration, and invasion capabilities in gastric cancer (GC) cells, while TM4SF18 knockdown effectively suppresses these capacities." (PMID 41404116, 2025).
pancreatic cancer (2 papers, 2019 to 2022). "To investigate a functional role of TM4SF18 in PDAC we developed stably-expressing inducible shRNA pancreatic cancer cell lines." (PMID 30897168, 2019). "We next assessed TM4SF18 expression in the pancreatic cancer cell lines Panc-1, MiaPaca-2, BxPC-3, AsPC1, and Capan-1, as well as the non-malignant human pancreatic ductal epithelium (HPDE) cell line by western blot analysis." (PMID 30897168, 2019). "To identify a role of TM4SF18 in pancreatic cancer cell biology we utilized doxycycline-inducible shRNA constructs to knockdown TM4SF18 in Capan-1 cells." (PMID 30897168, 2019). "The L6 members are known to have a role in cancer cell migration and thus we investigated if TM4SF18 drives pancreatic cancer cell migration." (PMID 30897168, 2019). "In summary, to our knowledge we provide the first evidence that TM4SF18 is expressed in normal and pancreatic cancer tissue including acinar tissue, pre-neoplastic ductal lesions, and tumor epithelium." (PMID 30897168, 2019). "TM4SF18 represents a promising novel biomarker and therapeutic target for pancreatic cancer." (PMID 30897168, 2019). "In addition, we define a regulatory role of TM4SF18 in pancreatic cancer cell growth." (PMID 30897168, 2019). "In recent years, both TM4SF18 and TM4SF1 are overexpressed in pancreatic cancer." (PMID 36209368, 2022). "TM4SF18 has been found to promote cell growth but not regulate migration in pancreatic cancer cells." (PMID 36209368, 2022). "Silencing of TM4SF18 did not significantly affect the migration of cells as compared to control Capan-1 cells suggesting that TM4SF18 is not involved in pancreatic cancer cell migration." (PMID 30897168, 2019).
atherosclerosis (1 paper, 2025). A disease characterized by the build-up of fatty material and calcium deposition in the arterial wall resulting in partial or complete occlusion of the arterial lumen. "Through further differential analysis and screening using machine learning algorithms, APLNR, PCDH12, PODXL, SLC40A1, TM4SF18, and TNFRSF25 were identified as key diagnostic genes for atherosclerosis." (PMID 40070840, 2025). "We determined that APLNR, PCDH12, PODXL, SLC40A1, TM4SF18, and TNFRSF25 are key genes associated with lipid metabolism in samples affected by atherosclerosis." (PMID 40070840, 2025). "In our study, we identified APLNR, PCDH12, PODXL, SLC40A1, TM4SF18, and TNFRSF25 as the most relevant genes associated with lipid metabolism and atherosclerosis, highlighting their potential as diagnostic and immune markers." (PMID 40070840, 2025). "Our study employed various machine learning algorithms to identify that APLNR, PCDH12, PODXL, SLC40A1, TM4SF18, and TNFRSF25, among the lipid metabolism genes, can serve as diagnostic markers in patients with atherosclerosis and are associated with atherosclerotic immune infiltration." (PMID 40070840, 2025). "The ROC curve was employed to assess the predictive potential of these key gene markers in atherosclerosis, revealing that the AUC values for APLNR, PCDH12, PODXL, SLC40A1, TM4SF18, and TNFRSF25 were 0.763, 0.859, 0.780, 0.807, 0.792, and 0.848, respectively." (PMID 40070840, 2025). "Through our investigation, we discerned the crucial functions of APLNR, PCDH12, PODXL, SLC40A1, TM4SF18, and TNFRSF25 within the framework of atherosclerosis." (PMID 40070840, 2025).
Skin Cutaneous Melanoma (1 paper, 2024). "TM4SF18 was substantially downregulated in BLCA, BRCA, KICH, LUAD, LUSC, PRAD, Skin Cutaneous Melanoma (SKCM)." (PMID 38206300, 2024).
cancer (2 papers, 2019 to 2024). A tumor composed of atypical neoplastic, often pleomorphic cells that invade other tissues. "There was a ~20-fold elevated expression of TM4SF18 in the cancer cell lines compared to the normal ductal cell line." (PMID 30897168, 2019). "In contrast, lower expression of TM4SF18 predicts a poor prognosis in various types of cancers." (PMID 38206300, 2024). "Xenograft tumor models will be important to further define the role of TM4SF18 in cancer biology." (PMID 30897168, 2019). "TM4SF18 is highly homologous to TM4SF1 but has yet to be studied in any aspect of cancer biology." (PMID 30897168, 2019). "Expression Atlas revealed that TM4SF1, TM4SF4, TM4SF18, and TM4SF19 were expressed in various cancer cell lines." (PMID 38206300, 2024).
tumor (2 papers, 2019 to 2022). "TM4SF18 was found to be involved in GC tumor progression through the EMT pathway by GSEA enrichment analysis." (PMID 36209368, 2022). "To investigate the relationship between TM4SF18 and tumor‐infiltrating immune cells and functions, we quantified the enrichment fractions of different immune‐related functions and pathways, and cell subpopulations using single‐sample GSEA." (PMID 36209368, 2022). "Although there is minimal expression in normal ducts, we observed increased TM4SF18 levels in preneoplastic ducts and tumor epithelium." (PMID 30897168, 2019). "Utilizing immunohistochemistry (IHC) and western blot analysis, our studies for the first time demonstrate that TM4SF18 is highly expressed in PDAC tumor epithelium." (PMID 30897168, 2019). "In addition, TM4SF18 is the only L6 family protein in the family known to promote tumor cell growth." (PMID 36209368, 2022). "Finally, we explored the relationship between TM4SF18 expression, tumor immune infiltration, and tumor microenvironment (TME)." (PMID 36209368, 2022). "It is unclear whether TM4SF18 is a factor involved in the transdifferentiation process or possibly co-opted to promote tumor cell growth." (PMID 30897168, 2019). "In contrast, TM4SF18 showed strong co-localization with the CK-19+ tumor epithelium." (PMID 30897168, 2019).
TM4SF18 also shares sentences with these, for which no sentence is quoted: adrenocortical carcinoma (1 paper); breast invasive carcinoma (1); cervical squamous cell carcinoma (1); diffuse large B-cell lymphoma (1); endocervical adenocarcinoma (1); hepatocellular carcinoma (1); hypothyroidism (1); lung adenocarcinoma (1); lymphoid neoplasm (1); ovarian serous cystadenocarcinoma (1); pancreatic adenocarcinoma (1); pancreatic ductal adenocarcinoma (1); thymoma (1); thyroid carcinoma (1).